KLF12 (KLF transcription factor 12)
Description:
Confers strong transcriptional repression to the AP-2-alpha gene. Binds to a regulatory element (A32) in the AP-2-alpha gene promoter.
Synonyms: AP2REP; HSPC122; AP-2rep
Tractability: PROTAC: ubiquitination databases record sites on it; its protein half-life has been measured.
Gene: Protein-coding gene on chromosome 13 (73,686,089 to 74,134,922, reverse strand). Ensembl gene ENSG00000118922.
Subcellular location: Nucleus
Subcellular location (Human Protein Atlas): Nucleoplasm; Cytosol
Gene Ontology:
Molecular function: chromatin-protein adaptor activity; DNA binding; DNA-binding transcription factor activity; DNA-binding transcription repressor activity, RNA polymerase II-specific; protein binding; RNA polymerase II cis-regulatory region sequence-specific DNA binding; sequence-specific double-stranded DNA binding; DNA-binding transcription factor activity, RNA polymerase II-specific; RNA polymerase II transcription regulatory region sequence-specific DNA binding
Biological process: negative regulation of transcription by RNA polymerase II; regulation of transcription by RNA polymerase II; chromatin organization
Cellular component: chromatin; nucleus
Genetic constraint (gnomAD): Loss-of-function variants: 6 observed, 29.74 expected, observed/expected ratio (o/e) 0.2, 90% interval 0.11 to 0.4. The upper end of that interval is the gene's LOEUF score, 0.4, which puts it in group 1 of 6, group 1 being the genes least tolerant of losing a copy. Missense variants: 329 observed, 460.55 expected, observed/expected ratio (o/e) 0.71, 90% interval 0.65 to 0.78. Synonymous variants: 184 observed, 188.36 expected, observed/expected ratio (o/e) 0.98, 90% interval 0.87 to 1.1.
Homologues: Orthologues: macaque KLF12 (100% identical), guinea pig KLF12 (99% identical), rabbit KLF12 (98% identical), chimpanzee KLF12 (98% identical), mouse Klf12 (97% identical), dog KLF12 (97% identical), rat Klf12 (94% identical), pig KLF12 (84% identical), tropical clawed frog klf12 (82% identical), zebrafish klf12b (69% identical), zebrafish klf12a (57% identical), Drosophila melanogaster luna (25% identical). Paralogues in human: KLF8 (38% identical), KLF3 (36% identical), KLF5 (27% identical), KLF7 (24% identical), KLF6 (24% identical), KLF4 (24% identical), KLF11 (23% identical), KLF2 (22% identical), KLF10 (21% identical), KLF1 (21% identical), KLF15 (21% identical), SP8 (20% identical), and 10 more.
Diseases named in the same sentence as KLF12 in open-access papers:
KLF12 is named in the same sentence as 52 diseases in open-access papers, as found by Europe PMC text mining. Sharing a sentence is not in itself a finding about the gene and the disease. The quoted sentences say what the papers report.
gastric cancer (19 papers, 2010 to 2026). A primary or metastatic malignant neoplasm involving the stomach. "For example, ENC-1, often over-expressed in some types of leukemia, KLF12, a transcription factor associated with progression of gastric cancer, and CDC42EP2, a small Rho GTPase binding protein involved in hypoxia-induced angiogenesis, were induced by gefitinib at 24 h treatment." (PMID 20579378, 2010). "Selective knockout of KLF12 can significantly induce growth retardation in the gastric cancer cell line HGC27." (PMID 37606530, 2023). "Previous studies have confirmed that miR/137 can regulate KLF12 in gastric cancer and pancreatic cancer." (PMID 33413360, 2021). "Krueppel-like factor 12 (KLF12) is a well-known oncogene in different kinds of human cancers such as pancreatic cancer, gastric cancer, and endometrial cancer." (PMID 34616917, 2021). "In gastric cancer (GC) tissues, miR-200a-3p plays a cancer suppressing role in GC by targeting KLF12." (PMID 32380777, 2020). "KLF12, one of the target genes with a higher predictive score, has been shown to be regulated by miR-137 in gastric cancer." (PMID 30866999, 2019). "KLF12 is frequently elevated in esophageal adenocarcinoma and has been reported to promote gastric cancer progression." (PMID 27442508, 2016). "For example, KLF12 expression was elevated in around 40% of poorly differentiated gastric cancers (GCs) and its levels correlated with tumor size." (PMID 27442508, 2016). "On the other hand, KLF12 was shown to induce cell proliferation, angiogenesis and invasion in gastric cancer cell lines and clinical samples." (PMID 24555920, 2014). "The two loci (DOCK10 and FCN1-FCN2) replicated from CoGaPro1, and the 11 loci replicated from CoGaPro2 (CDK15, CROCC2-SNED1, TLR2-RNF175-SFRP2, WWC2, RELN, ZMYM5-ZMYM2, KLF12, SKAP1, CABLES2, and MIR630) gave further support for these genes being associated with a risk of CRC and gastric cancer." (PMID 41516419, 2026). "Circ-RNF111 aggravates gastric cancer malignancy through mir-876-3p-dependent KLF12 regulation." (PMID 40426921, 2025). "KLF12 plays an important role in the malignant progression of poorly differentiated gastric cancer." (PMID 37606530, 2023). "In addition, miR-137 targets KLF12 and MYO1c in gastric cancers to inhibit tumorigenesis." (PMID 34539732, 2021). "In gastric cancer, high TTN‐AS1 expression contributed to the poor OS and tumor progression by the TTN‐AS1‐miR‐376b‐3p‐KLF12 axis." (PMID 37528740, 2023). "In addition, KLF12 promoted gastric cancer (GC) cell proliferation and invasion in vitro." (PMID 27442508, 2016). "Krüppel-like factor 12 (KLF12) is a transcription factor that plays a role in normal kidney development, and KLF12 is frequently elevated in esophageal adenocarcinoma and has been reported to promote gastric cancer progression and also to be involved in colorectal cancer." (PMID 41516419, 2026). "Several studies had showed that Myosin 1 C (MYO1C) may play a key role in regulatingautophagosome–lysosome fusion through F-actin remodeling, and miR-137 overexpression inhibited the cell migration, proliferation by targeting Krűppel-likefactor 12 (KLF12) and MYO1C in gastric cancer cell lines." (PMID 34488531, 2021).
cervical carcinoma (13 papers, 2017 to 2023). A carcinoma arising from either the exocervical squamous epithelium or the endocervical glandular epithelium. "KLF12 expression was significantly down-regulated in patients with ovarian cancer, endometrial cancer, and cervical cancer." (PMID 36983713, 2023). "Mechanistically, circNEIL3 indirectly upregulated the expression of oncogene KLF12 by suppressing the expression of oncogene miR-137, which ultimately enhanced the proliferation of cervical cancer cells, while inhibiting circNEIL3 produced the opposite result." (PMID 36497204, 2022). "Compared with the healthy women, KLF12 expression was significantly downregulated in patients with ovarian cancer, endometrial cancer, and cervical cancer." (PMID 34950609, 2021). "A luciferase reporter assay showed that circNEIL3 adsorbed miR-137 and upregulated KLF12 to regulate the proliferation of cervical cancer cells." (PMID 33413360, 2021). "In cervical cancer, circNEIL3 promotes tumorigenesis through the regulation of KLF12 by acting as a ceRNA of miR-137." (PMID 34348712, 2021). "In conclusion, circNEIL3/miR-137/KLF12 can form a ceRNA network to regulate the proliferation of cervical cancer cells." (PMID 33413360, 2021). "Some hotspot genes (e.g., KLF5, LRP1B, and KLF12) have previously been described in cervical cancer, and others (e.g., CADM2, CEP19, CSMD1, and NRROS) are reported for the first time in the present study." (PMID 34885212, 2021). "Subsequent molecular mechanism analysis revealed that circNEIL3 was an oncogene that served as the ceRNA to indirectly upregulate KLF12 expression by competitively binding with miR-137, thus promoting the proliferation of cervical cancer cells." (PMID 33413360, 2021). "Recently, a whole-genome sequencing study on HPV-positive SiHa, HeLa and cervical carcinoma cells showed KLF12 was one of the top three integration sites for HPV." (PMID 33225922, 2020). "In addition, rescue experiments confirmed that KLF12 blocked the effect of circNEIL3 on improving the proliferation of cervical cancer." (PMID 33413360, 2021). "Based on this mechanism, we believe that circNEIL3/miR-137/KLF12 may be a promising and novel biomarker and therapeutic target for cervical cancer." (PMID 33413360, 2021). "Furthermore, a previous study reported that KLF12 protein is highly expressed in cervical cancer cells." (PMID 34644678, 2021). "In summary, circNEIL3 is an oncogene and might serve as ceRNA, which competitively binds to miR-137, thereby indirectly upregulating KLF12 expression and promoting the proliferation of cervical cancer cells." (PMID 33413360, 2021). "CircNEIL3 is an oncogene in cervical cancer and might serve as a ceRNA that competitively binds to miR-137, thereby indirectly upregulating the expression of KLF12 and promoting the proliferation of cervical cancer cells." (PMID 33413360, 2021). "Furthermore, we used the HPA database to validate KLF12 expression in cervical cancer and normal cervical tissues." (PMID 34950609, 2021). "However, whether KLF12 plays a direct role in cervical cancer and whether its inhibition can promote cervical tumorigenesis remains unclear." (PMID 34950609, 2021). "The HGT-ID workflow also identified an HGT candidate downstream of KLF12, a tumor suppressor gene, in both the SIHA cervical cancer cell line and a tumor sample." (PMID 30016933, 2018). "In HPV-positive cervical cancer, viral genome integrations occur on all chromosomes, with no detectable hot spots, except for the KLF5/KLF12 gene and adjacent to the MYC gene locus." (PMID 31766658, 2019).
ovarian carcinoma (12 papers, 2017 to 2024). A malignant neoplasm originating from the surface ovarian epithelium. "Therefore, we inferred that ISG15 was downregulated by KLF12 via binding with the CACCC element in cisplatin‐resistant ovarian cancer cells, implicated in maintenance of CSC‐like features." (PMID 33797839, 2021). "Immunohistochemical (IHC) and in situ hybridization (ISH) assays confirmed that miRNA-141 expression is inversely correlated with KLF12 expression and significantly associated with advanced ovarian cancers accompanied with distal metastases, underscoring the clinical relevance of our findings." (PMID 28095864, 2017). "The expression of KLF12 was decreased in ovarian cancer and endometrial cancer, suggesting its role as a biomarker for gynecological tumor monitoring." (PMID 36983713, 2023). "In other cases, KLF12 expression was correlated positively with disease severity such as in colorectal cancer, lung cancer, ovarian cancer, and endometrial cancer, indicating its tumor-promoting effect." (PMID 34950609, 2021). "MiR-141/KLF12/Sp1/survivin signaling pathway enhanced AR in ovarian cancer, and a transcriptomic study addressed the importance of CDKN1A-regulated quiescence for cells to survive from anoikis in head and neck squamous carcinoma." (PMID 34456997, 2021). "In fact, KLF12 has been previously reported to be targeted by miR-141 to strengthen anoikis resistance to facilitate ovarian cancer metastasis." (PMID 32958011, 2020). "Another study found that overexpression inhibits apoptosis by targeting the Kruppel-like factor 12 (KLF12) gene in ovarian cancer cells." (PMID 33447132, 2020). "In ovarian cancer, miRNA-141 enhances the anoikis resistance of metastatic ovarian carcinoma cell by regulating Kruppel Like Factor 12/Sp1 Transcription Factor (KLF12/Sp1) axis." (PMID 32782028, 2020). "But depletion of survivin by shRNAi approach remarkably reduced anoikis resistance of ovarian cancer cells and suppressed their tumor colonization in peritoneal cavity of mice, suggesting survivin is the major downstream effector of miR-141/KLF12." (PMID 28095864, 2017). "Taken together, our study revealed that the overexpression of miR-141 augments anoikis resistance in ovarian cancer cells by targeting and repressing the expression of KLF12, which, in turn, competes for binding sites in the survivin promoter with Sp1." (PMID 28095864, 2017). "This suggests that miR-141 protects ovarian cancer cells from anoikis by suppressing KLF12 expression." (PMID 28095864, 2017). "IHC analysis on ovarian cancer tissue array was used to evaluate the expressions of KLF12 and miR-141 and to show the clinical relevance." (PMID 28095864, 2017). "In this study, we showed that the upregulation of miR-141 and the subsequent suppression of KLF12 are essential for anoikis resistance in ovarian cancer cells both in vitro and in vivo." (PMID 28095864, 2017). "Besides, the expression of KLF12 was also decreased in ovarian cancer and endometrial cancer, suggesting its role as a biomarker for gynecological tumor monitoring." (PMID 34950609, 2021). "Besides, miR-141 can increase resistance against detachment-induced cell death by inhibiting KLF12 expression in ovarian cancer." (PMID 33820555, 2021). "Western blot also demonstrated that KLF12 increased in cisplatin‐resistant ovarian cancer cells." (PMID 33797839, 2021). "As there is an inverse relationship between KLF12 and miR-141, KLF12 may play an opposing role in ovarian cancer cell tumorigenicity and may have relatively low expression." (PMID 28095864, 2017). "Importantly, the inverse correlation between miR-141 and KLF12 expression was clinically confirmed of that the miR-141/KLF12/Sp1/survivin is a new signaling axis required for anoikis resistance of ovarian cancers during metastatic progression." (PMID 28095864, 2017).
ovarian carcinoma (continued). "In addition, miR-141-3p is overexpressed in ovarian cancer tissues, and this miRNA can augment anchorage-independent cell growth and anoikis resistance by suppressing the expression of Kruppel-like factor 12 (KLF12), which interferes with Sp1-activated transcription of the survivin gene." (PMID 33435156, 2021). "Furthermore, using a Human Apoptosis Array Kit consisting of 35 apoptosis-related proteins (R&D) with either miR-141-overexpressing or KLF12 knockdown ovarian cancer cells, 8 out of 35 proteins (HO-2/HMOX2, ph-Rad 17, CIAP-2, survivin, HSP-70, TNFR1/TNFRSF1A, clusterin and XIAP) were upregulated." (PMID 28095864, 2017). "Obvious negative correlation of ISG15 was observed with KLF12 (R = −0.287, P = 1.25e−8) in 379 ovarian cancers." (PMID 33797839, 2021). "Our data indicated that downregulating ISG15 expression, via weakening effect of KLF12, might be considered as new therapeutic strategy to inhibit CSC phenotypes in the treatment of cisplatin‐resistant ovarian cancer." (PMID 33797839, 2021). "Western blot analyses indicated that Sp1 could significantly elevate the expression levels of survivin as well as XIAP, while KLF12 had the opposite effects compared to Sp1 and suppressed survivin and XIAP expressions in both ovarian cancer cell lines." (PMID 28095864, 2017). "Hence, we speculated that the miR-141-induced anoikis resistance is mediated through suppression of KLF12, which, in turn, upregulates survivin and XIAP expression to inhibit ovarian cancer cell apoptosis." (PMID 28095864, 2017).
colorectal cancer (10 papers, 2016 to 2026). A primary or metastatic malignant neoplasm that affects the colon or rectum. "In colon cancer, KLF12 promotes the growth of colorectal cancer through EGR1 (early growth response protein 1)." (PMID 34644678, 2021). "The oncogenic function of KLF12 has been elucidated in several cancers, such as colorectal cancer, pancreatic cancer, osteosarcoma, and nasopharyngeal carcinoma." (PMID 34461926, 2021). "While, KLF12 can directly activate the expression of early growth response protein 1 to promote the colorectal cancer growth." (PMID 31709048, 2019). "Here, we examined the role of KLF12 in colorectal cancer (CRC)." (PMID 27442508, 2016). "Collectively, these findings revealed that miR-382 inhibits migration and enhances chemosensitivity by targeting KLF12 and HIPK3 in colorectal cancer." (PMID 29700213, 2019). "Furthermore, we identified Krüppel-like factor 12 (KLF12) and homeodomain-interacting protein kinase 3 (HIPK3) as the target of miR-382, and miR-382 rescued the promotion effect of KFL12 on migration and enhanced chemosensitivity in colorectal cancer cell lines." (PMID 29700213, 2019). "Indeed, we examined whether PGE2 induced KLF12 expression and found that PGE2 did not affect the expression of KLF12 in colorectal carcinoma cells (data not shown)." (PMID 27442508, 2016).